UCA1 (urothelial cancer associated 1)
Diseases named in the same sentence as UCA1 in open-access papers (continued):
Sharing a sentence is not in itself a finding about the gene and the disease.
pancreatic cancer (continued). "This study aims to investigate the expression level and prognostic value of UCA1 in pancreatic cancer tissues, the effects and mechanism of UCA1 in regulating cell proliferation, apoptosis and metastasis." (PMID 37564930, 2023). "Through interacting with miR-96, the lncRNA UCA1 promoted cellular proliferation and suppressed apoptosis and metastasis in pancreatic cancer." (PMID 37245177, 2023). "Several studies have showed that the expression of UCA1 is up-regulated in pancreatic tumor tissues and PaC cell lines 31-39." (PMID 36741256, 2023). "Together with previous reports of UCA1 upregulation in liver and pancreatic cancers as well as CEBPA-AS1 in liver cancer, our results suggest that these plasma RNAs can be universal tumour markers for the diagnosis of gastrointestinal cancers." (PMID 35186077, 2022). "LncRNA UCA1 was also reported to be highly expressed in exosomes derived from hypoxic pancreatic cancer cells." (PMID 35444652, 2022). "Hypoxia promotes the release of exosomes from pancreatic stellate cells for the delivery of UCA1 to pancreatic cancer cells." (PMID 36499136, 2022). "More recently, exosomal UCA1 was proven to be released from hypoxic pancreatic cancer cells and transported to endothelial cells, in which UCA1 relieves the activity of miR-96-5p on AMOTL2." (PMID 35055115, 2022). "We also showed that knockdown of lncRNA UCA1 inhibited tumorigenesis in mice xenografting with pancreatic cancer cells." (PMID 34868904, 2021). "The exosomes were isolated from PSCs and hypoxic PSCs (HPSCs), and co-cultured with pancreatic cancer cells transduced with manipulated lncRNA UCA1, EZH2, and SOCS3." (PMID 34868904, 2021). "Corroborating previous documentation, our results confirmed through gain- and loss- of function assays that lncRNA UCA1 inhibited the expression of SOCS3, thereby enhancing the malignant phenotypes, tumorigenesis and Gem resistance of pancreatic cancer cells." (PMID 34868904, 2021). "We then moved to illustrate the downstream mechanism of the effect of lncRNA UCA1 in pancreatic cancer." (PMID 34868904, 2021). "Some studies have also reported that lncRNA UCA1 is highly expressed in pancreatic cancer tissues and plays a carcinogenic role in tumor proliferation and metastasis." (PMID 34868904, 2021). "We also identified that the low expression of MEG3, LINC01963, and LINC00261 and the high expression of MACC1-AS1, LINC00462, LINC01559, and UCA1 were significantly correlated with worse survival in pancreatic cancer patients." (PMID 34827663, 2021). "In pancreatic cancer, cancer cells under hypoxic conditions can release high levels of exosomes carrying lncRNA UCA1." (PMID 34819615, 2021). "EZH2 overexpression occurred in pancreatic cancer and it was positively correlated with lncRNA UCA1 expression." (PMID 34868904, 2021). "Multiple studies have indicated that UCA1 acts as a ceRNA in developing and progressing pancreatic cancer in multiple axes." (PMID 35047414, 2021). "Further, hypoxic exosomal lncRNA UCA1 has been found to promote drug resistance, angiogenesis, and tumor growth in pancreatic cancer." (PMID 34868904, 2021). "In contrast, upregulation of lncRNA MACC1-AS1, LINC00462, LINC01559, and UCA1 predicted shorter overall survival in pancreatic cancer patients." (PMID 34827663, 2021). "The high expression of exosomal lncRNA UCA1 promoted the malignant phenotypes, and augmented the Gem resistance of pancreatic cancer." (PMID 34868904, 2021). "This study aims to investigate roles of lncRNA UCA1-loaded exosomes secreted by pancreatic stellate cells (PSCs) in Gemcitabine (Gem) resistance of pancreatic cancer under hypoxia, which involves the methylation of SOCS3 and EZH2 recruitment." (PMID 34868904, 2021). "LncRNA UCA1 facilitates the migration and invasion of pancreatic cancer cells through Hippo signaling pathway." (PMID 32239639, 2020).
pancreatic cancer (continued). "UCA1 was up-regulated in pancreatic cancer tissues and correlated with poor clinical outcome, and promoted cell migration and invasion by the Hippo signaling pathway." (PMID 30250401, 2018). "UCA1 is upregulated in multiple cancers, including bladder, endometrial and pancreatic cancer and acts as an oncogenic lncRNA." (PMID 28715488, 2017). "Higher lncRNA UCA1 expression was also reported as an independent prognostic biomarker for pancreatic cancer and glioma." (PMID 28969100, 2017). "Additionally, UCA1 overexpression in pancreatic cancer enhances PDAC cells’ stemness and cell proliferation by splashing miR-590-3p and interacting with hnRNPA2B1 to increase oncogenic KRAS expression and activation." (PMID 39201351, 2024). "Moreover, UCA1 directly targets miR-135a to promote the growth and dissemination of pancreatic cancer cells." (PMID 39201351, 2024). "UCA1 is subsequently transported to pancreatic cancer cells by these exosomes." (PMID 38911968, 2024). "UCA1 acted as an oncogene in pancreatic cancer by partly regulating miR-582-5p/BRCC3, which could be a new therapeutic target for pancreatic cancer." (PMID 37564930, 2023). "UCA1 also aided pancreatic cancer growth by decreasing miR-135a expression." (PMID 37245177, 2023). "Our study investigated the regulatory role of UCA1 in pancreatic cancer." (PMID 37564930, 2023). "In this article, we review the abnormal expression, molecular mechanism, and clinical significance of UCA1 in pancreatic cancer, which might provide theoretical basis for the potential future clinical applications." (PMID 36741256, 2023). "Survival analysis of pancreatic cancer samples showed that low expression of UCA1, TM4SF1-AS1, LINC00941, DNMBP-AS1, and CASC8 improved OS more than high expression, whereas high expression of SNHG10 and SOCS2-AS1 improved OS more than low expression (P < 0.001)." (PMID 36871072, 2023). "In this review, we address the biological function and regulatory mechanism of UCA1 in pancreatic cancer, which might give a new approach for clinical diagnosis and treatment." (PMID 36741256, 2023). "Five lncRNAs (LINC00941, UCA1, CASC8, TM4SF1-AS1, and DNMBP-AS1) were more strongly expressed in the high-risk group than in the low-risk group, suggesting that they are the potential risk factors for pancreatic cancer." (PMID 36871072, 2023). "Interestingly, lncRNA UCA1 was also enriched in exosomes derived from pancreatic stellate cells (PSCs), and such exosome was able to promote the Gemcitabine resistance of pancreatic cancer cells through SOCS3/EZH2 Axis." (PMID 35444652, 2022). "Furthermore, pancreatic cancer-derived exosomal UCA1 has been found to promote tumor angiogenesis by targeting miR-96; exosomal UCA1 modulates cervical cancer stem cell self-renewal and differentiation by targeting miR-122." (PMID 36483681, 2022). "When internalized by HUVECs, exosomal UCA1 from hypoxic pancreatic cancer cells can inhibit miR-96-5p, upregulate the expression of its target gene AMOTL2, and subsequently activate the ERK signaling pathway, which promotes the migration and tube formation of HUVECs19." (PMID 34819615, 2021). "The results showed that lncRNA UCA1 was highly expressed in pancreatic cancer samples." (PMID 34868904, 2021). "In conclusion, the exosomes secreted by hypoxia-activated PSCs could deliver lncRNA UCA1 to pancreatic cancer cells." (PMID 34868904, 2021). "In addition, Pearson’s correlation analysis showed that SOCS3 expression was negatively correlated with the expression of EZH2 (r = -0.75, p < 0.01) and lncRNA UCA1 (r = -0.73, p < 0.01) in pancreatic cancer tissues." (PMID 34868904, 2021). "UCA1 targets miR‐107 to promote pancreatic cancer progression." (PMID 32767514, 2020). "UCA1 expression has been proposed to be a potential biomarker for bladder and pancreatic cancer." (PMID 31061680, 2019). "The tumour-specific expression of UCA1 is a potential biomarker for bladder and pancreatic cancer." (PMID 31061680, 2019).
pancreatic cancer (continued). "In pancreatic cancer, there were only two studies assessing the correlation between UCA1 expression and clinicopathological data, the following clinicopathological features were both reported in the two studies: gender, location, histological grade, nervous invasion and depth of tumor." (PMID 28380443, 2017). "UCA1 could be a potential therapeutic target and prognostic marker for pancreatic cancer." (PMID 37564930, 2023). "CASC8, DNMBP-AS1, LINC00941, TM4SF1-AS1, and UCA1 expression was positively correlated with risk scores, indicating that they are risk factors for pancreatic cancer; in contrast, SNHG10 and SOCS2-AS1 were negatively correlated, thus serving as protective factors for pancreatic cancer." (PMID 36871072, 2023). "Finally, we proceeded to determine whether HPSC-EXO affects the chemotherapy resistance of pancreatic cancer through the lncRNA UCA1/EZH2/SOCS3 axis." (PMID 34868904, 2021). "In addition, several ncRNAs such as AFAP1-AS1, UCA1, HOTAIR, PVT1, MALAT-1, circ-ADAM9, BC008363, circ-LDLRAD3, circ-IARS, circ-PDE8A, circ_0030235, and circ_0001649 have been associated with prognosis of pancreatic cancer." (PMID 34439315, 2021). "Therefore, the present study set out to elucidate the roles of lncRNA UCA1 loaded in PSC-derived exosomes in Gem resistance of pancreatic cancer under hypoxia, and to identify the downstream mechanisms involving histone methylation in SOCS3 gene region and EZH2 recruitment." (PMID 34868904, 2021). "Additionally, YAP stimulated the expression of UCA1 in pancreatic cancer cells." (PMID 34178644, 2021). "In addition, lncRNA UCA1 expression was found not only to be increased in hypoxic pancreatic cancer cells, but also enriched in exosomes derived from hypoxic pancreatic cancer cells, and it was established that lncRNA UCA1 knockout restricted angiogenesis and tumor growth." (PMID 34868904, 2021). "However, the regulatory role and mechanism of UCA1 in pancreatic cancer remain unknown." (PMID 37564930, 2023). "Meanwhile, numerous studies have revealed the involvement of lncRNA in gemcitabine resistance in pancreatic cancer, including PVT1, HIF1A-AS1, UCA1, etc.." (PMID 36371178, 2022). "The delivered UCA1 recruits EZH2 to modulate the level of histone methylation in the SOC3 gene region, which increases the resistance of pancreatic cancer cells to gemcitabine." (PMID 36499136, 2022). "The results of qRT-PCR showed higher expression of lncRNA UCA1 and EZH2 and lower SOCS3 expression in pancreatic cancer tissues than that in adjacent normal tissues." (PMID 34868904, 2021). "By recruiting EZH2, lncRNA UCA1 regulates the methylation of SOCS3 protein, reduces the expression of SOCS3, and promotes the Gem resistance of pancreatic cancer." (PMID 34868904, 2021). "In vitro and in vivo experimental results confirmed that lncRNA UCA1-loaded HPSC-EXO promoted malignant phenotypes, inhibited apoptosis, and promoted Gem resistance of pancreatic cancer cells as well as tumorigenesis in mice." (PMID 34868904, 2021). "UCA1 can interact with hMOB1, LATS1, and YAP to form shielding composites, thereby allowing YAP activation in pancreatic cancer cells." (PMID 31185650, 2019). "In addition to UCA1, several other lncRNAs have been shown to modulate KRAS downstream signalling in pancreatic cancer." (PMID 40427100, 2025). "UCA1 was elevated in EVs obtained from hypoxic compared with normoxic pancreatic carcinoma cells and in serum-derived EVs from pancreatic carcinoma patients." (PMID 35966580, 2022). "Overall, UCA1 and YAP promoted invasion of pancreatic cancer cells." (PMID 34178644, 2021). "A study on 80 patients with pancreatic cancer showed that high expression of lncRNA AFAP1-AS1 and UCA1, and low expression of ENSG00000218510 could predict poor overall survival and tumor progression in pancreatic cancer." (PMID 34439315, 2021).
pancreatic cancer (continued). "Under hypoxic conditions, exosomes secreted by hypoxia-induced PSCs deliver lncRNA UCA1 into pancreatic cancer cells, where lncRNA UCA1 recruits EZH2 and regulates histone methylation level in SOCS3 gene region, thereby augmenting pancreatic cancer resistance to Gem." (PMID 34868904, 2021). "LncRNA UCA1 was highly expressed, while SOCS3 was poorly expressed in pancreatic cancer tissues." (PMID 34868904, 2021). "Because of little heterogeneity and small number of included studies, publication bias and sensitivity analysis were not performed in analyzing the relationship between UCA1 and clinicopathological parameters of pancreatic cancer." (PMID 28380443, 2017). "A ceRNA network profile has identified the several lncRNAs for classifying diabetic pancreatic cancer form non-diabetic pancreatic cancer, including HOTAIR, CECR7, UCA1, suggesting that lncRNAs are important predictors for diabetic pancreatic cancer." (PMID 36313695, 2022). "Similarly, UCA1 was found to be a robust prognostic marker for diabetic pancreatic cancer, whilst both HOTAIR and UCA1 were involved in separate lncRNA/miRNA/lncRNA “competitive triples” that could stratify diabetic and non-diabetic pancreatic cancer patients with high accuracy." (PMID 29702599, 2018).
prostate carcinoma (40 papers, 2014 to 2025). A carcinoma that arises from epithelial cells of the prostate gland. "The lncRNA UCA1 is one such case where it interacts with miR-184 via a sponging mechanism for causing cellular proliferation for prostate cancer." (PMID 37245177, 2023). "For discriminating D'Amico high‐risk from low‐ and intermediate‐risk prostate cancer patients, the UCA1 score showed some usefulness." (PMID 35289508, 2022). "The UCA1 score of high‐risk prostate cancer patients is dramatically higher than that of benign patients (median 0.455 vs. −2.630, p < 0.0001)." (PMID 35289508, 2022). "To improve early detection and risk prediction of prostate cancer, we incorporated the urine urothelial carcinoembryonic antigen 1 (UCA1) gene expression levels and the serum PSA level." (PMID 35289508, 2022). "We aimed to explore the role of long noncoding RNA urothelial carcinoma-associated 1 (lncRNA UCA1) and its underlying mechanism in the radioresistance of prostate cancer (PCa)." (PMID 32943997, 2020). "The prostate cancer–associated UCA1 gene has a transcript isoform promoted from an LTR7c, as well as an additional internal RIDL, thereby making a potential link between cancer gene regulation and RIDLs." (PMID 30587508, 2019). "Specifically, the UCA1 score may be of great diagnostic significance for suspected prostate cancer patients with low or intermediate PSA levels." (PMID 35289508, 2022). "In conclusion, we systematically determined and validated that a novel UCA1 score could serve as a new noninvasive test for early detection and risk prediction of prostate cancer." (PMID 35289508, 2022). "To determine if UCA1 expression was associated with outcomes in PCa, we first investigated UCA1 expression in the Canadian Prostate Cancer Genome Network (CPC-GENE) data, which includes sequencing data from a cohort of 209 patients with intermediate-risk PCa treated with RT or radical prostatectomy." (PMID 27902466, 2017). "Therefore, we explored whether the UCA1 score can be used as a potential biomarker for prostate cancer detection or risk prediction." (PMID 35289508, 2022). "For example, miR-494-3p has been shown to inhibit CXCR4 expression after transcription processes in prostate cancer; lncRNA UCA1 activates CXCR4 through inhibiting the activity of miR-204 to promote the progression of prostate cancer." (PMID 37190171, 2023). "Compared with SelectMDx, another well‐known urine marker study for prostate cancer, our Shengli training cohort showed that the UCA1 score had a better AUC (0.880 vs. 0.76) and PPV (0.67 vs. 0.27)." (PMID 35289508, 2022). "Based on the recommended UCA1 score threshold of ≥−0.475 (sensitivity and specificity were optimal), 150 of 517 patients were identified with prostate cancer." (PMID 35289508, 2022). "Combining PSA <4 with UCA1 score ≥−0.475, all nine of 62 patients were successfully diagnosed with prostate cancer and 70.97% of prostate biopsies were excluded." (PMID 35289508, 2022). "In prostate cancer, LncRNA UCA1 can upregulate MYO6 expression to exert oncogene activity, and it needs to “sponge” miR‐143 for upregulation." (PMID 35592755, 2022). "By sponging miRNA-204, lncRNA UCA1 promotes expression level of CXCR4 to enhance metastasis of prostate cancer cells." (PMID 35773731, 2022). "In patients with PSA <4, combined with UCA1 scores ≥−0.475, nine of 62 patients were successfully diagnosed with prostate cancer." (PMID 35289508, 2022). "UCA1 also regulates the growth and metastasis of prostate cancer by a competing endogenous RNA mechanism that regulates the miR‐204–CXCR4 axis." (PMID 35289508, 2022). "At a cutoff value of UCA1 score ≥−0.475, 112 of 380 patients were diagnosed with prostate cancer with a sensitivity of 0.714 and a specificity of 0.837." (PMID 35289508, 2022). "LncRNA UCA1 which mapped on chr19 has been demonstrated involved in many different tumors such as non-small cell lung cancer, renal cell carcinoma, prostate cancer, and so on." (PMID 33832120, 2021).